IL6 (interleukin 6)
Diseases named in the same sentence as IL6 in open-access papers (continued):
Sharing a sentence is not in itself a finding about the gene and the disease.
glioma (continued). "Inflammatory markers like IL-6, CRP, SAA, and TNF-α can induce M2 macrophage polarization, promoting glioma progression and playing an essential role in glioma development." (PMID 41244525, 2025). "We found the conditioned medium (CM) from GL261 or ALTS1C1 mouse glioma cell-activated BV2 cells, whereas R-2HG treatment specifically inhibited the production of IL-6." (PMID 41367876, 2025). "We found that CM from GL261 or ALTS1C1 mouse glioma cells significantly induced BV2 cells and primary microglial activation by increasing the expression of cytokines such as IL-6 and TNFα." (PMID 41367876, 2025). "CNOT7 regulates the progression of glioma by affecting the E2F targets, G2/M checkpoint, TNF-α and IL6-JAK-STAT3 signaling pathway through NF-κB, leading to poor prognosis in glioma." (PMID 41249119, 2025). "We highlight signaling axes such as IL-6/STAT3, NF-κB, and TGF-β that connect immune dysregulation to epigenetic instability and the emergence of glioma-initiating cells." (PMID 41403936, 2025). "IL-6 induces myeloid PD-L1 expression in GBM, and disruption of IL-6 signaling in orthotopic murine glioma models decreased local and peripheral myeloid-mediated immunosuppression and promoted antitumor immunoactivity." (PMID 40507329, 2025). "Senescent glioma cells upregulate SASP genes and secrete a panoply of SASP factors, prominently interleukin IL-6, an activator of the JAK-STAT3 pathway." (PMID 39972068, 2025). "For instance, human astrocytes secrete IL-6, which in turn up-regulate the expression of matrix metalloproteinase-14 (MMP14) in glioma cells." (PMID 40345526, 2025). "Another feedforward mechanism involves glioma-derived MCP-1/CCL2, which triggers the release of IL-6 from microglia, a ligand for signal and activator of transcription 3 (STAT3) pathway in gliomas." (PMID 38254796, 2024). "We found that overexpression of CSMD1 in glioma cells resulted in a decrease in phosphorylation of both P65 and STAT3 as well as a decrease in secretion of both IL-6 and IL-8 when compared to the corresponding Ctrl glioma cells." (PMID 38561856, 2024). "The results showed that the mRNA expression levels of STAT3 (P < 0.01), IL-6 (P < 0.01), and TNF-α (P < 0.01) were significantly increased in glioma samples compared with paracancerous tissues." (PMID 38495483, 2024). "The levels of serum factors IL-4, IFN-α, IFN-γ, IL-6, TNF-α, CCL4, CCL11, and VEGF were found to be significantly higher in gliomas compared with inflammatory diseases of the central nervous system (p < 0.05)." (PMID 39364412, 2024). "The gene expression level of both IL6 and CXCL8 was also downregulated in the CSMD1-high group compared to the CSMD1-low group in glioma cohorts." (PMID 38561856, 2024). "Glioma-derived CCL2 acts on microglia, triggering IL-6 production, which in turn promotes GBM invasion." (PMID 38732975, 2024). "Various inflammatory cytokines, including TNF, CSF2, IL1A, IL17A, IL6, and IFNG, were predictively inhibited in glioma samples exhibiting high CSMD1 expression." (PMID 38561856, 2024). "In contrast, levels of IL-4, IFN-α, IFN-γ, IL-6, TNF-α, CCL4, P-cadherin, TRAIL, CCL11, and VEGF were significantly higher in serum than in CSF for both glioma and brain inflammation groups." (PMID 39364412, 2024). "And in our study, we found that the mRNA expression levels of IL-6, TNF-α, and STAT3, which are important factors in the STAT3 signaling pathway, were significantly increased in glioma samples." (PMID 38495483, 2024). "Glioma-activated myeloid cells secrete Th17-promoting cytokines, including IL-1β, TGF-β, IL-6, and IL-23, and have a major impact on the induction of intratumoral Th17 cells in TME." (PMID 38918274, 2024). "In glioma TME, glioma cells can secrete granulocyte macrophage colony-stimulating factor(GM-CSF), IL-6, IL-10 and other cytokines to stimulate the expansion of MDSC." (PMID 39334448, 2024).
glioma (continued). "We subsequently quantified the levels of IL-6 and IL-8 secreted in the supernatant using ELISA after two hours of TNF treatment of glioma cells, as STAT3 was observed to be upregulated at that time point." (PMID 38561856, 2024). "IL6 promoted the proliferation of GBM cells, and a high level of IL6 predicted poor prognosis of glioma." (PMID 38322416, 2024). "Glioma cell-intrinsic TIM-3 is involved in inducing macrophage migration and transition to anti-inflammatory/pro-tumorigenic phenotype by a TIM-3/interleukin 6 (IL6) signal." (PMID 37567938, 2023). "It has been shown that interleukin-6 (IL-6) can promotes MSC tropism to cancer sites and also this movement is IL-8-dependent in glioma." (PMID 36829187, 2023). "Several factors, including STI1, EGF, CSF-1, CCL2, IL-6, TGF-β and TGF-β2, are released from TAMs and can promote glioma proliferation and/or migration." (PMID 37705736, 2023). "The mutual activation between glioma cells can be inhibited by a nanomedicine (i.e., Nano-DOX), which inhibits STAT3 activation in glioma cells, thereby abolishing IL-6-mediated STAT3 cross-activation in astrocytes and its promotion of glioma cells." (PMID 36923251, 2023). "Previous study explored the TMSB10 promoted glioma progression via YAP1/AKT/ERK1/2, but we explored the TMSB10 promoted glioma progression via IL6/JAK/STAT3 signaling pathway." (PMID 37275863, 2023). "Out of these NRGs, 19 NRGs (EGLN3, HILPDA, HMBS, HYOU1, BNIP3, etc.)were found to be enriched in glioma tissues while 13 genes (SLC4A1, IL6, EPAS1, ACE, HMOX1, etc.)were decreased compared to normal tissues." (PMID 37934582, 2023). "In addition, the GSVA revealed that epithelial-mesenchymal transition, IL6-JAK-STAT3 signaling, IL2-STAT5 signaling, interferon-gamma response, allograft rejection, and coagulation Hallmark gene sets were expressed at a higher level in cluster 2 gliomas of both IDH subtypes." (PMID 36970537, 2023). "As an example, interleukin-6 (IL-6) can enhance MSC attraction to cancerous areas, whereas MSC migration in glioma is dependent on IL-8." (PMID 37667271, 2023). "DAMPs induces microglia in the area surrounding tumor necrosis to express IL-1β in a TLR-mediated manner, which induces glioma cells to release a range of cytokines such as CXCL8,CCL2, IL-1β and IL-6." (PMID 37700840, 2023). "Factors like interleukin-6 (IL-6) and IL-8 released by the tumor can enhance MSC attraction to cancerous areas and glioma, respectively." (PMID 37667271, 2023). "Taken together, IL-6 and miR-155-3p delivered by “hypoxic” exosomes derived from human GBM cells drive macrophages towards an immunosuppressive phenotype which supports glioma proliferation and migration." (PMID 36555253, 2022). "Inhibitor of differentiation 3 (ID3)-induced increases in IL-6 and IL-8 are significantly decreased by treatment with an EGFR inhibitor that directly dephosphorylates AKT in glioma cells." (PMID 36341365, 2022). "Using multiplex cytokine/chemokine analysis, these authors further demonstrated that nuclear IL-33 facilitates tumour growth by triggering glioma-mediated expression of inflammatory cytokines (LIF, IL-6, IL-8, IL-1RN, IL-1β and secreted IL-33." (PMID 36555253, 2022). "Caspase-8 can also stimulate the NF-kB pathway and upregulate the secretion of IL-8, IL-1β, IL-6, VEGF and MCP-1, improving temozolomide resistance in gliomas." (PMID 36605437, 2022). "The expression of proinflammatory cytokines such as TNF-α, IL-6 and IL-1β induced by LPS treatment was dose-dependently attenuated in IOE-treated C6 glioma cells." (PMID 36670940, 2022). "GAMs have been shown to release a number of factors that stimulate tumor growth and invasion, including TGF-β, IL-1β, IL-6, stress-inducible protein 1 (STI1), and EGF, by acting on GICs in the perivascular niche and glioma cells." (PMID 35448036, 2022). "The activation of IL6/JAK/STAT3 pathway between tumor-initiating cells and macrophages has been shown to lead to poor outcomes in glioma patients." (PMID 36341390, 2022).
glioma (continued). "Preclinical and clinical investigations showed that IL6-JAK-STAT3 pathway inhibition has therapeutic benefits in cancer and that STAT3 inhibition inhibits the growth of glioma cells." (PMID 36105094, 2022). "It has been reported that an activity change in the IL6/JAK/STAT3 signaling pathway can regulate liver hepatocellular carcinoma, chronic myeloid leukemia, and glioma." (PMID 36118871, 2022). "In this glioma–TIM crosstalk, glioma cells produce cytokines, such as CCL2, GM-CSF, and IL-6, that promote chemoattraction, recruitment, and maturation of myeloid cells in the tumor microenvironment." (PMID 35884700, 2022). "We previously reported that glioma GL261 cells subjected to PS-PDT and co-cultured with DCs induced the production of IL-6, indirectly supporting our current RNA-seq data." (PMID 36539408, 2022). "It was reported that glioma initiating CD133(+) cells and Mφs/microglia cointeraction activated expression of B7-H4 via IL6-activated STAT3, thereby blocking effective T-cell immune responses within the microenvironment of gliomas." (PMID 36685508, 2022). "In the microenvironment of glioma and in the tumor microenvironment, the EGFR and the IL6 signaling pathway play important roles in activating STAT3." (PMID 35783263, 2022). "Gliomas produces cytokines that can recruit MDSCs (i.e. CCL2, CXCL8, SDF-1, CXCL2), as well as cytokines that induce MDSCs expansion (i.e., IL-6, PGE2, IL-10, GM-CSF)." (PMID 36186781, 2022). "Glioma initiates the interaction between CD133+ cells and Mφs/microglia and activates the expression of B7-H4 in tumor cells and in the TME through IL-6 and IL-10." (PMID 36466873, 2022). "In the glioma microenvironment, GAM perpetuate CD4+/CD8+ T cell apoptosis through secretion of CD95, the ligand for the T cell death receptor Fas, and IL-6, a potent inducer of Fas." (PMID 34884869, 2021). "The CD90low gaMSC subpopulation, which is a newly identified recruited component in the tumour microenvironment, secreted IL-6, which then upregulated FOXS1 expression and activated the EMT process, thus contributing to TMZ resistance in glioma cells." (PMID 34256854, 2021). "We identified microglia-derived EGF, PDGFβ, SDF-1α, and IL-6 as the primary activators driving Pyk2 and FAK activation in glioma." (PMID 34944779, 2021). "TAMs have been shown to release a plethora of factors that stimulate tumor growth and invasion, including TGF-β, IL-1β, IL-6, stress-inducible protein 1 (STI1), and epidermal growth factor (EGF) by acting on GSCs in the perivascular niche and glioma cells." (PMID 33766119, 2021). "Glioma cells express multiple immune-suppressive cytokines such as transforming growth factor-beta (TGF-β), IL-10, IL-4, IL-6, and IL-13, all of which interfere directly or indirectly with anti-glioma immune response." (PMID 34084145, 2021). "Wogonin also inhibits the progression of gliomas by downregulating the secretion of the inflammatory cytokines TNF-α, IL-6, and IL-1β." (PMID 33897434, 2021). "At present, radiotherapy plays an important role in the treatment of glioma, but significantly increases CXCL1, IL‐6 and IL‐8 amounts." (PMID 34216174, 2021). "Pro‐inflammatory factors have been described in glioma, and it is generally considered that IL‐6, IL‐8, CXCL1, CXCL10 and TGFβ2 are pro‐tumour cytokines closely related to glioma progression." (PMID 34216174, 2021). "Based on these results, EGF, PDGFα, PDFGβ, IL-6, IL-8, and SDF-1α were selected as candidates for the microglial regulation of Pyk2 and FAK signaling in glioma cells." (PMID 34944779, 2021). "Inhibitors of the corresponding receptors, DMPQ, burixafor, tocilizumab, and reparixin, eliminated the stimulatory effect of MCM on IF and IA, supporting the involvement of PDGFβ, SDF-1α, IL-6, and IL8 in MCM-induced CL1 glioma cell invasion." (PMID 34944779, 2021).
glioma (continued). "In glioma TIME, IL6-JAK-STAT3 signaling pathway acts a critical role in driving tumor cell proliferation, invasion, and metastasis and negatively regulates immune response." (PMID 34650972, 2021). "We identified microglia-derived PDGFβ, EGF, SDF-1α, IL-6, and IL-8 as factors involved in the activation of Pyk2 and FAK signaling in glioma cells." (PMID 34944779, 2021). "The macrophage-induced vascular mimicry in gliomas cells is dependent on IL-6 and COX2 induction in gliomas and GBM cells, respectively." (PMID 33783686, 2021). "We finally analyzed The Cancer Genome Atlas (TCGA) data sets to investigate the role of IL-6 and CD40 in human patients with GBM or glioma." (PMID 34103524, 2021). "Similar to IL-6, EGR1 expression was reduced in glioma cells transfected with TMEM44-AS1, whereas overexpression of TMEM44-AS1 increases EGR1 expression." (PMID 34696771, 2021). "Based on these results, we suggest that EGF, IL-6, SDF-1α, and PDGFβ together orchestrate Pyk2 and FAK regulation in glioma cells, leading to cell cycle activation." (PMID 34944779, 2021). "EGF and IL-6 together, and to some extent also with SDF-1α and PDGFβ, play a role in enhancing glioma cell mitosis and viability." (PMID 34944779, 2021). "Our results expand on those of previous studies indicating that the activation of Pyk2 and FAK in gliomas is induced by microglia-derived EGF, PDGFβ, SDF-1α, IL-6, and IL-8." (PMID 34944779, 2021). "We also confirmed significantly positive correlations between HOXB5 and IL6 expression in each WHO grade glioma and among the total glioma samples." (PMID 33858489, 2021). "Meanwhile, IL‐6 and CXCL1 were obviously increased in the course of glioma radiotherapy, and the inflammatory activity was obviously enhanced by transcriptome analysis of radiotherapy resistance." (PMID 34216174, 2021). "Glioma initiates CD133(+) cells and the macrophages/microglia cointeraction activates the expression of B7-H4 (B7x/B7S1), a B7 family member, via IL6 and IL10 in both tumor cells and microenvironment-supporting cells." (PMID 34071306, 2021). "In C6 glioma cells, the chaperone activity of HSPB1 contributed to the production of the pro-inflammatory cytokine, IL-6, whereas T cells from HSPB1−/− mice exhibited reduced secretion of TNF and IL-2." (PMID 33423680, 2021). "Survival was lower in patients with high expression of TGF-β, IL6, and CD133 in both the glioma samples and TCGA database than in other patients." (PMID 33576874, 2021). "Tang el al. observed that, in glioma patients, while only 5.8% of peripheral NKT expressed IL-6 and IL-10, 92.4% of cells in glioma tissues were IL-6+ IL-10+." (PMID 32178454, 2020). "After the inhibition of STAT3 is released, IL-6 activates the STAT3 signal cascade, which leads to an increase in the expression level of VEGF in glioma and contributes to tumor vessel formation." (PMID 33511267, 2020). "Our subsequent experiments documented that EZH2 upregulation contributed to M2 macrophage polarization in glioma by downregulating PTEN through miR-454-3p-dependent promotion of PTEN, characterized by IL-6 downregulation and IL-8 and MIP-3α upregulation." (PMID 33363140, 2020). "We therefore analyzed plasma IL-6, YKL-40, and genetic variation in YKL-40 and explored their ability to distinguish between glioma subtypes and predict survival in GBM." (PMID 32363159, 2020). "Together with IL6, IL10 and FGF are also known to activate STAT3, which was found to be constitutively activated in glioma." (PMID 33153019, 2020). "The results demonstrated that infection with Lenti-EZH2 in glioma cells appreciably reduced the expression of MIP-3α and IL-8 and increased the expression of IL-6 in co-cultured M2 macrophages." (PMID 33363140, 2020). "For example, in glioma, via the MYD88-TLR4 pathway, glioma stem cells stimulate the TAMs to produce IL-6, which, in turn, will stimulate the EMT via the JAK/STAT3/Snail pathway." (PMID 33228048, 2020).
glioma (continued). "ANXA2P2 was positively correlated with genes that are related to glioma proliferation, invasion and angiogenesis, such as ANXA2, CD44, IL6, MMP14, MMP9, and VEGFA." (PMID 31681595, 2019). "AP-2α was found to suppress classically activated (M1) macrophages producing the cytokine IL-6 and Jak2/STAT3 activation and subsequently decrease PD-L1 expression in glioma cells." (PMID 31534499, 2019). "Meanwhile, several GAM-derived factors such as TGF-β, stress-inducible protein (STI)-1, IL-6, IL-1β, and EGF have been identified as promoters of glioma cell invasion." (PMID 29389898, 2018). "We found that the levels of IL6 and IL6R expression were significantly higher in mesenchymal subtypes of glioma compared with classical, neural, and proneural subtypes, respectively." (PMID 29258522, 2017). "Compared with the classical, neural, and proneural glioma cells, the levels of IL6 and IL6R mRNA and protein expression were higher in mesenchymal glioma cells." (PMID 29258522, 2017). "Two genes contributing to the malignant progression of various cancer types notably gliomas WHO grade II–IV, IL6 and STAT3, were modulated by either molecules." (PMID 28467792, 2017). "Tocilizumab showed the capacity to inhibit the growth of U87MG glioma cell, and suppressed the in vivo growth of human oral squamous cell carcinoma (OSCC) by inhibiting IL-6/STAT3 and angiogenesis signaling pathways." (PMID 28927416, 2017). "In glioma cells, NFAT1 enhanced the promoter activities of IL6R and IL6, and upregulated the expression of both IL6R and IL6." (PMID 29258522, 2017). "Therefore, the hypoxia/IL-6/lncTCF7 axis may be a potential target for glioma therapy." (PMID 29234033, 2017). "In line with this, the amount of IL6 correlated with HIF1A levels and tumor grade in glioma tissues." (PMID 28459042, 2017). "GSCs upregulate interleukin 6 (IL6) release from microglia via toll-like receptor 4 (TLR4) signaling, which enhances invasion and glioma growth." (PMID 28670569, 2017). "In our present study, activation of the TLR4 signaling pathway promoted the production of IL-1β, IL-6, IL-10, MCP-1, MIP-1α, and TNF-α in glioma CD133+ CSCs." (PMID 28881826, 2017). "In the present study, using TCGA database and patient-derived primary glioma cells, we found both IL6 and IL6R expression were significantly correlated with mesenchymal subtype and IDH-wildtype gliomas, and were predictors for unfavourable prognosis." (PMID 29258522, 2017). "In gliomas, upregulation of IL6 expression correlates with poor patient survival, while ablation of IL-6 prevents glioma formation in a mouse model." (PMID 29258522, 2017). "Increased expression of IL-6 and MMP14 was first validated in primary human glioma specimens and then correlated with various clinical parameters." (PMID 27613828, 2016). "IL-6 was also the key cytokine inducing cytomembrane MMP14 expression, the active form of MMP14, in glioma cells." (PMID 27613828, 2016). "Taken together, these results demonstrate that IL6 expression correlates with the density of autophagic cells and HIF1A levels in high-grade (WHO III and IV) gliomas." (PMID 27163161, 2016). "In glioma cells the expression of miR-92a generates tolerant natural killer T cells (NKT) and also promotes the expression of IL-10 and IL-6 in these cells, showing a reduction of perforin, Fas ligand, and interferon-γ." (PMID 27294132, 2016). "We found that Stattic blocked the IL6- and hypoxia-induced upregulation of MIR155-3p in U251 and T98G glioma cells." (PMID 27163161, 2016). "LPS induced ROS in U-87 human glioma cells which allevated pro-inflammatory cytokines (TNF-α, IL-6 and IL-1β)." (PMID 27435304, 2016). "Both increased IL-6 and MMP14 expression correlated with advanced WHO grade and poor overall survival in glioma patients." (PMID 27613828, 2016). "Among these cytokines, IL-6 was found to be the most significantly increased factor in media from NHA, especially from NHA in co-culture with glioma cells." (PMID 27613828, 2016).